IL18 (interleukin 18)
Diseases named in the same sentence as IL18 in open-access papers (continued):
Sharing a sentence is not in itself a finding about the gene and the disease.
pancreatitis (18 papers, 2012 to 2025). Inflammation of the pancreas. "Moreover, pyroptosis promotes severe pancreatitis and associated lung injury through the release of cytokines IL-1β and IL-18, and is implicated in acute myocardial injury and spinal cord injury." (PMID 39717896, 2024). "The levels of pro-inflammatory interleukin IL-18 are also elevated in obese subjects, and simultaneous treatment with IL-12 and IL-18 causes severe acute pancreatitis in obese mice but only edematous pancreatitis in control mice." (PMID 23028532, 2012). "Results indicated that IL-6, IL-18, and IL-1β were all significantly elevated in pancreatitis samples." (PMID 40787634, 2025). "IL-1β, TNF-α, IL-6, IL-8, and IL-18 are widely reported pro-inflammatory cytokines that are key indicators for the early prediction and diagnosis of pancreatitis." (PMID 35663952, 2022). "The activation of NLRP3 inflammasome will deteriorate inflammation of pancreatitis, and esults in production of IL-1β, IL-18, and HMGB1, which are associated with systemic injury." (PMID 33967799, 2021). "The simultaneously increase in NF‐κB and IL‐18 levels due to interferon‐γ in pancreatitis also provides a possible relationship between the factors and pancreatic diseases." (PMID 32347623, 2020). "Regarding Fxr-dependent genes implicated in intestinal barrier function: Angiogenin-1 (Ang1) mRNA expression in the ileum was reduced in the early pancreatitis group, whereas iNos, Car12 and Il18 were similar in all groups." (PMID 25470824, 2014). "In the present report, we used the IL-12+ IL-18 murine model of AP to investigate the effect of RGZ in modulating severity of pancreatitis in mice fed a low fat diet (LFD) or high fat diet (HFD)." (PMID 22815875, 2012). "In addition, quantitative real-time PCR and ELISA analysis showed that the levels of IL-5, IL-18, and the chemokines eotaxin-1 and eotaxin-2 transcripts and proteins were significantly increased in cerulein-induced pancreatitis." (PMID 36969002, 2023). "Notably, IL18 plus IL12 administration is a well-characterized model of experimental pancreatitis in obese mice, emphasizing the importance of IL18 in the pathophysiology of the disease." (PMID 32751171, 2020). "Acute severe pancreatitis was induced by IL-12 + IL-18 injections in ob/ob mice as detailed above." (PMID 28986573, 2017). "Since activin is increased in animals after sham-operations, we used a non-invasive induced model of AP, in which IP injections of IL-12 + IL-18 on subsequent days lead to aggressive necrotizing AP in ob/ob mice and a mild, edematous pancreatitis in wild-type animals." (PMID 28986573, 2017). "We previously reported an increased level of IL-18 in the tissue of experimental pancreatitis, and in the current report, we showed induced NLRP3, IL-18, and eosinophils in a murine model of CP." (PMID 34183442, 2021). "Therefore, after GQD intervention, the production of NLRP3 can be inhibited, thereby reducing the synthesis of Caspase-1 and GSDMD, lowering the release of inflammatory factors such as IL-1β and IL-18, and increasing IL-10 levels, thereby preventing the progression of post ERCP pancreatitis." (PMID 40620677, 2025).
periodontal disease (18 papers, 2014 to 2026). "The interactions of IL-10, IL-12, and IL-18 are implicated in the progression of periodontal disease." (PMID 39080003, 2024). "Four studies identified that the presence of IBD and periodontal disease was associated with higher levels of prostaglandin E2, aMMP8, IL-18 and S100A12, respectively, when compared to patients without the coexistence of both diseases." (PMID 34501547, 2021). "Furthermore, in T2DM there is an increase in TNF-α, IL-1β, IL-6, and IL-18, which are known to elevate HbA1C, which increases the risk for periodontal disease." (PMID 37629193, 2023). "Therefore, the association between IL-18 rs187238 and rs1946518 polymorphisms and periodontal disease remains controversial." (PMID 36289627, 2022). "Orthodontic force loading regulates the inflammatory reactions in periodontal disease by up-regulating the production of various pro-inflammatory mediators, including IL-18 and its receptors, which increases bone resorption." (PMID 40724937, 2025). "As periodontal disease advances, there is a proportional increase in the concentration of IL-18 in GCF." (PMID 39080003, 2024). "Determining the exact role of IL-18 in the pathogenesis of periodontal diseases requires further research." (PMID 36289627, 2022). "In vivo, when using IL-18 transgenic (Tg) mice, IL-18 overexpression was related to periodontal disease." (PMID 31065235, 2019). "It is reported that IL-18 levels in gingival crevicular fluid are elevated in sites of periodontal disease." (PMID 25866631, 2014). "The results from our study population suggest that the IL-18 rs187238 and rs1946518 polymorphisms are not significant factors influencing the risk of periodontal disease." (PMID 36289627, 2022). "IL-18, a pro-inflammatory cytokine, might be responsible for the initiation and progression of periodontal disease." (PMID 36013509, 2022). "IL-18 may stimulate the process of osteogenesis and it may also inhibit bone resorption intensified in patients with periodontal disease, and thus slow down the disease process." (PMID 36289627, 2022). "Lower levels of IL-18 have been noted in early periodontal disease as compared to healthy controls." (PMID 35844512, 2022). "Moreover, the statistical analysis denoted significant correlations between the GCF IL-18 levels and the parameters of periodontal disease's severity (periodontal probing depth, clinical attachment loos, and gingival bleeding index), similar to those highlighted by other papers." (PMID 34840527, 2021). "Increased expression of NLRP3 and AIM2 in the gingival tissues of patients with periodontal disease is positively correlated with the levels of IL-1β and IL-18, suggesting that various inflammasomes may participate in the microbial-induced inflammation in periodontal diseases." (PMID 32385413, 2020). "Rats with ligature-induced periodontal disease with OTM have shown significantly higher IL-18 gene and protein expression than those without OTM." (PMID 40724937, 2025). "To date, no studies have examined the relationship between the IL-18/IL-10 ratio and periodontal diseases." (PMID 39080003, 2024).
rheumatic diseases (18 papers, 2017 to 2025). "The proinflammatory cytokine IL-18, implicated in the induction of NETosis, was similarly elevated in the four rheumatic diseases." (PMID 41465552, 2025). "Blood circulation levels of IL-18 are elevated in both patients with SJIA and AOSD, and significantly increased during episodes of MAS; this significant elevation in IL-18 diagnostically distinguishes MAS flares from underlying rheumatic disease." (PMID 38775430, 2024). "Inflammasome-derived IL-18/IL-1β were suggested to play important roles in MAS-associated rheumatic diseases." (PMID 34239943, 2021). "The results of this study confirm a proinflammatory state and elevated IL-18 levels in rheumatic diseases." (PMID 41465552, 2025). "There are currently four ongoing clinical trials of IL-18 blocking medications in relevant rheumatic diseases." (PMID 38183056, 2024). "Our current research suggests the need for further studies on the role of IL-18 in the pathogenesis of vascular injury in rheumatic diseases, including JIA." (PMID 35160217, 2022). "Serum IL-18 levels in AOSD patients were statistically higher than those in any of the rheumatic diseases in those studies." (PMID 34691064, 2021). "Thus, IL-18, a cytokine that promotes NETosis, is approximately equally elevated in the rheumatic diseases analyzed." (PMID 41465552, 2025). "In their study, a significant elevation of IL-18 serum levels in active AOSD and systemic onset juvenile idiopathic arthritis (sJIA) was found in comparison with other rheumatic diseases, and a clear association of IL-18 serum levels with disease activity in AOSD was evidenced." (PMID 34948117, 2021). "Repeated monitoring of serum IL-18 levels was useful in distinguishing elderly AOSD from other disorders, including infectious and collagen diseases." (PMID 35839054, 2022). "Marked increase of proinflammatory cytokines including IL-1, IL-6, IL-18, TNFα, IFNγ, ferritin and ST2 during MAS attacks portrayed a significant systemic inflammation in patients with various rheumatic diseases, particularly sJIA28,44–47." (PMID 34099791, 2021). "Levels of IL-18, reflecting inflammasome activation, have been reported to be markedly increased in MAS and only moderately elevated in other rheumatic disease and in familial HLH." (PMID 33568193, 2021). "Altogether, results from this study set the stage for future studies to characterize the in vivo function of this novel antibody in clinical studies of IL-18-mediated diseases such as MAS, IBD, and rheumatic diseases." (PMID 33823154, 2021). "This study gives further evidence to earlier publications of elevated IL-18 serum levels in active AOSD and sJIA, with up to 1000-fold higher concentrations compared to other rheumatic diseases." (PMID 30886992, 2019). "Additionally, the comparison to tumor-agnostic indications may not translate sufficiently to complex rheumatic diseases wherein the induction and effects of IL-18 may differ by disease." (PMID 38183056, 2024).
hyperlipidemia (17 papers, 2014 to 2025). "The current study is the first to report the association between IL-18 SNPs and hyperlipidemia in the Chinese Han population." (PMID 38774744, 2024). "In the present study, we aim to investigate the relationship between IL-18 single nucleotide polymorphisms (SNPs) and hyperlipidemia in the Han Chinese population in Taiwan." (PMID 38774744, 2024). "In mice, IL-18 deficient mice develop hyperlipidemia and subsequent NASH." (PMID 37342340, 2023). "In this study, swimming, as a treatment, reduced the expression of NLRP3, caspase-1, and IL-18, thereby indicating that exercise can act as a protective agent against hyperlipidemia-induced neuronal injury." (PMID 34409103, 2021). "In addition, exercise reduced the hyperlipidemia-induced increase in the expression of inflammatory signals, including IL-1β, IL-6, and IL-18, in kidney tissue." (PMID 37277452, 2023). "Our data confirmed that increased hyperlipidemia-mediated inflammation activated HMGB1-TLR4 signaling, NLRP3 inflammasome formation, and upregulation of pyroptosis markers caspase-1, IL-1β, IL-18, and the pyroptosis executor GSDMD." (PMID 36829889, 2023). "In case of liver inflammation related genes (IL-1β, TNF-α, IL-6, IL-18, CCL20, and NF-κB) their expression levels were significantly (P < 0.05) upregulated and IL-1RN was significantly (P < 0.05) downregulated in the liver of hyperlipidemia group." (PMID 41144456, 2025). "Moreover, HLF could significantly reduce the levels of NLRP3, caspase-1, IL-1β, IL-6, IL-18, and TNF-α and increase the activities of plasma SOD, CAT, and GSH-PX, which suggested that HLF could effectively relieve the inflammatory response and oxidative stress induced by hyperlipidemia." (PMID 36425260, 2022).
Infertility (17 papers, 2012 to 2025). "Single nucleotide polymorphisms were employed as instrumental variables to examine the causal relationships between MDD, genetically predicted IL-18 levels, and infertility." (PMID 40226698, 2024). "The most important finding in our study is the role of IL-18 as a partial mediator in this association, contributing to ~12.70% of the infertility risk attributable to MDD." (PMID 40226698, 2024). "Our finding that levels of IL-18 were relatively low in unexplained infertility patients might then reflect an underlying perturbed immunological profile for this infertility cause." (PMID 22007253, 2012). "Interestingly, the levels of both follicular IL-8 and IL-18 increased as follicles grew (adjusted for age and cause of infertility r = 40.2 pg/mL, P = 0.005, and r = 1 3.1 pg/mL for every additional millimeter in diameter, P = 0.022, resp)." (PMID 22007253, 2012). "In contrast, findings from an earlier study indicated higher IL-18 levels in fragmented chromatin structures in the semen of males experiencing infertility." (PMID 40806758, 2025). "Through mediating MR, we aim to quantify the proportion of MDD's effect on infertility mediated through IL-18, shedding light on intermediary mechanisms." (PMID 40226698, 2024). "This research has suggested a link between major depressive disorder (MDD) and infertility, with interleukin-18 (IL-18) being proposed as a potential mediator due to its connections to both conditions." (PMID 40226698, 2024). "The study utilizes both two-sample and multivariable MR to isolate specific effects of MDD and IL-18 on infertility, controlling for pleiotropic influences where genetic variants affect multiple traits." (PMID 40226698, 2024). "Elevated IL-18 levels have been associated with conditions like endometriosis and PCOS, both of which are linked to infertility." (PMID 40226698, 2024). "Increased levels of inflammatory mediators in the endometrium of infertile patients, including IL-12, IL-15, IL-18, and IL-27, have the potential to influence uNK cell responses and to attract peripheral NK cells." (PMID 32872526, 2020). "We evaluated IL-18 levels in the serum and follicular fluid of infertile women undergoing IVF or ICSI." (PMID 27747236, 2016). "However, it is important to mention that the exact mechanisms by which IL-18 influences infertility are not fully understood." (PMID 40226698, 2024). "Furthermore, IL-18 levels were elevated during the luteal phase compared to the follicular phase, but they did not differentiate between women with pelvic pain and those with infertility." (PMID 39767772, 2024). "All these findings suggest that IL18 could be a relevant player not only in EM pathogenesis, but also in EM-related infertility mechanisms, defining it as a promising molecular target to be implemented, in a long-term perspective, as a predictive and diagnostic biomarker." (PMID 37626618, 2023). "Cytokines like interleukin 1β (IL-1β), IL-6, IL-10, IL-18, tumor necrosis factor α (TNF-α), interferon g (IFN-g), and transforming growth factor β1 (TGF-β1) are notably elevated in idiopathically infertile males and those with varicocele." (PMID 40070583, 2025). "Regarding the mediating role of IL-18 in the link between MDD and infertility, our initial findings suggested a partial mediation effect." (PMID 40226698, 2024). "The ROC curve analysis indicated strong and significant predictive power of IL-18, AIM-2, and NLRC-4/IPAF gene expressions in differentiating between NOA vs. NS patients and NOA vs. OA infertile men." (PMID 39712014, 2024). "Importantly, IL-18 has been suggested to favor ovarian folliculogenesis; a positive correlation has been reported between the level of follicular IL-18 and the number of retrieved oocytes and implantation success in women with different etiologies of infertility." (PMID 22007253, 2012).
Infertility (continued). "FF IL-18 is thought to be important for folliculogenesis as levels correlate with the number of oocytes retrieved in IVF cycles, in addition FF IL-18 levels are low in patients with unexplained infertility compared to patients with tubal factor infertility." (PMID 24040238, 2013). "Unlike previous studies that have shown elevated IL-18 levels in patients associated with female infertility conditions like PCOS, our MR study found high levels of IL-18 appeared to be protective against infertility." (PMID 40226698, 2024). "Furthermore, considering the mediating role of IL-18, exploring anti-inflammatory interventions as adjunctive treatments for MDD-related infertility could be beneficial." (PMID 40226698, 2024). "Notably, IL-18's mediation was particularly pronounced in infertility cases with cervical, vaginal, and other or unspecified origins, accounting for ~14.61% of the MDD-infertility link." (PMID 40226698, 2024).
sarcoidosis (17 papers, 2006 to 2026). Sarcoidosis is a multisystemic disorder of unknown cause characterized by the formation of immune granulomas in involved organs. "We evaluated MIF in the serum and bronchoalveolar lavage (BAL) fluid of sarcoidosis patients in association with clinical features and cytokines, IL-18, IL-10, IL-6, IFN-γ." (PMID 36207373, 2022). "To understand the regulation of group of cytokines implicated in sarcoidosis, we assessed the levels of IL-6, IL-18, IFN-γ and MIF in the serum samples of sarcoidosis patients (n = 65) and healthy controls (n = 28) via ELISA." (PMID 36207373, 2022). "Studies in Japanese patients with sarcoidosis suggest that IL-18 gene polymorphisms may be associated with an increased genetic risk of developing sarcoidosis." (PMID 36314034, 2022). "There are theories regarding a link between sarcoidosis and cytokines, including Th1, IL-2, IL-6, IL-8, IL-12, IL-18, IL-27, interferon gamma, and tumor necrosis factor." (PMID 40259952, 2025). "IL-18 was found to be increased significantly in both BALF and blood samples of sarcoidosis patients, pointing towards a potential role of IL-18 in the pathophysiology of pulmonary sarcoidosis." (PMID 37334374, 2023). "Previous studies have shown elevated IL-18 in sarcoidosis BAL fluids, in serum and in response to microbial constituents." (PMID 36207373, 2022). "IL-18 belongs to IL-1 family of cytokines produced by monocytes and macrophages that has been shown to be increased in sarcoidosis patients." (PMID 36207373, 2022). "Here, we found that there is a significant heterogeneity among sarcoidosis patients with respect to serum cytokine profile, including IL-18, IFN-γ, IL-10 and MIF." (PMID 36207373, 2022). "Sarcoidosis patients expressed significantly (p = 0.05) higher levels of IL-18 (median = 209 pg/mL) as compared to healthy controls (median = 160 pg/mL), despite two healthy controls exhibited higher IL-18 (842 and other 527 pg/mL)." (PMID 36207373, 2022). "Our study group has recently showed a shift versus local Th1 immunologic response in sarcoidosis expressed by upregulation of two major Th1cytokines, IL-12 and IL-18." (PMID 20169144, 2009). "Serum IL-18 levels were measurable in almost all sarcoidosis patients." (PMID 36207373, 2022). "Thus, we analyzed serum IL-18 levels in sarcoidosis patients and healthy controls, and found that they were significantly higher in sarcoidosis patients than in healthy controls (247 ± 27 pg/mL vs. 122 ± 8 pg/mL, P = 0.0001)." (PMID 31515495, 2019). "In addition, the level of CD69 expression on MAIT cells was positively correlated with the IL-18 concentration in the serum of sarcoidosis patients (r = 0.431, P = 0.01)." (PMID 31515495, 2019). "In addition, concentrations of cytokines such as interleukin (IL)-12, IL-18, and IL-27, which promote the Th1 response, are increased in sarcoidosis tissues." (PMID 31515495, 2019). "Similarly, sarcoidosis has been shown to be associated with particular alleles in BTNL2, IL18, and IFNa, and SLC11A1." (PMID 16608528, 2006). "Additionally, serum amyloid A (SAA), which is highly expressed by macrophages in sarcoidosis granuloma, may play an important role in sarcoidosis via modulating the production of IL-18 and TNF." (PMID 35819638, 2022). "Similarly, in the present study, serum IL-18 levels were significantly higher in sarcoidosis patients than in healthy controls, and we observed a significant correlation between the serum IL-18 concentration and CD69 expression level on MAIT cells in peripheral blood." (PMID 31515495, 2019). "For a long time, sarcoidosis was seen as a Th1-driven disease, because of the variety of type 1 specific cytokines present in BALF and serum of sarcoidosis patients, including IFN-γ, IL-12, and IL-18." (PMID 32760396, 2020). "The overstimulation of cytokines, such as IL-12, IL-18, IL-27, and interferon (IFN)-gamma, has been postulated in lung sarcoidosis pathogenesis." (PMID 31358038, 2019).